EGFR (epidermal growth factor receptor)
Diseases named in the same sentence as EGFR in open-access papers (continued):
Sharing a sentence is not in itself a finding about the gene and the disease.
metastatic disease (continued). "The clinical importance of EGFR and its association with survivals were analyzed using three cohorts from MSKCC Prostate Oncogenome Project dataset (For primary tumors, n = 181; for metastatic tumors n = 37) and The Cancer Genome Atlas Prostate Adenocarcinoma Provisional dataset (n = 495)." (PMID 30134822, 2018). "Whether in non-selected patients, or in patients with EGFR mutations or wild-type EGFR patients, OS for patients with recurrent disease was superior to patients with locally advanced or metastatic disease." (PMID 28079142, 2017). "For example, the discordance of KRAS and BRAF mutations due to genetic diversification of metastatic cells compared to their primary tumor, may explain the lack of efficacy and the emergence of subsequent resistance when treating metastatic disease with EGFR monoclonal antibodies." (PMID 25902072, 2015). "Therefore, the convergence of panelists opinion toward the anticipation of KRAS testing in order to ensure the timely use of the most appropriate and personalized therapy in metastatic disease means that an anti-EGFR therapy should be extensively considered in metastatic KRAS wt tumors." (PMID 24465771, 2014). "In cases in which the primary tumors show EGFR mutations, the corresponding metastatic tumors may not show EGFR mutations." (PMID 24212826, 2011). "However, it is still uncertain whether the EGFR protein expression determined in the primary tumors exactly reflects the EGFR status of the metastatic tumors in NSCLC patients." (PMID 20096104, 2010). "Antibody‐based treatments in HNSCC, such as cetuximab (epidermal growth factor receptor; EGFR monoclonal antibody) or pembrolizumab (CD274; also known as PD‐L1 monoclonal antibody) are approved, but mostly in the recurrent/metastatic disease." (PMID 40437743, 2025). "Cetuximab, an epidermal growth factor receptor (EGFR) monoclonal antibody, is FDA-approved as a radiosensitizer for recurrent or metastatic disease, either alone or in combination with chemotherapy." (PMID 40885971, 2025). "Firstly, despite our focus on patients with oligo-residual NSCLC and EGFR/ALK wildtype, there remains inherent heterogeneity, such as driver gene alteration status, histology, overall disease burden, metastatic disease interval, and previous systemic therapy." (PMID 41213939, 2025). "The treatment of EGFR-mutant NSCLC has completely changed after the introduction of osimertinib in clinical practice, both in metastatic disease and in locally advanced/early stages." (PMID 40002263, 2025). "We feel that the combination of AA therapy, IO, and cytotoxic therapy may be beneficial for non-small-cell lung cancer (NSCLC) in the setting of metastatic disease without targetable mutations, brain metastases, locally advanced disease, and for recurrent EGFR-mutated (EGFRmut) disease." (PMID 39766108, 2024). "This review demonstrates the potential benefits of anti-angiogenic therapy in combination with chemotherapy and immunotherapy (AIC) as a viable strategy for treating EGFR-mutant, TKI-resistant, and de novo metastatic disease in NSCLC patients." (PMID 39766108, 2024). "We found seven DEGs (CCND1, EGFR, ENTPD5, HOXA10, IGF1R, MYC, and SNAI2) related to metastatic disease." (PMID 35806108, 2022). "In 48% and 71% of the cases, there were discordance in the expression of EGFR or one or more HER family members in paired primary and related metastatic tumours, respectively." (PMID 33562755, 2021). "Recent therapeutic approaches that add epidermal growth factor receptor (EGFR) and VEGF targeted agents to standard chemotherapy have produced a prolonged overall survival (OS) of up to 30 months in patients with metastatic disease." (PMID 31608230, 2019).
metastatic disease (continued). "Currently, epidermal growth factor receptor (EGFR) is the major target for therapeutic antibodies and inhibitor-based palliative treatment regimens aiming at controlling recurrent and metastatic disease in HNSCC patients." (PMID 30261040, 2018). "First-line treatments for patients with metastatic disease include FOLFIRI and FOLFOX, which have been combined with anti-EGFR or anti-VEGF antibodies to achieve benefit in selected populations." (PMID 29029527, 2017). "Patients with unresectable metastatic disease are eligible for targeted therapies such as inhibitors of vascular endothelial growth factor (VEGF) and epidermal growth factor receptor (EGFR)." (PMID 27999270, 2016). "Immunotherapy with the EGFR-specific IgG1 mAb, CTX, significantly improves survival of SCCHN patients with advanced or metastatic disease." (PMID 27884140, 2016). "CD15/FUT4 acts as a downstream regulator of MAPK-ERK pathway independently of EGFR or VEGF pathway, by coupling mitogenic signaling cascade and immune-escape mechanisms of metastatic tumors." (PMID 26427914, 2015). "Although the difference of EGFR mutation status in primary and metastatic tumors has been reported, the quantitative difference (ratio of mutated EGFR among total EGFR) in primary and metastatic tumors as well as in different sites of primary tumors was not clear." (PMID 24398248, 2014). "In patients with metastatic disease, decreased PFS correlated with p110α expression (P=0.024), whereas for OS were the presence of vascular invasion and EGFR expression (P⩽0.019; Cox analysis)." (PMID 22454081, 2012). "We found that patients with primary tumours showing alterations in EGFR and PTEN/PI3K/Akt had shorter PFS and OS despite trastuzumab treatment when given at advanced stage (metastatic disease), supporting their role in the mechanisms of response." (PMID 22454081, 2012). "EGFR and HER2 were expressed in circulating tumor cells of 38% and 50% patients with early and 44% and 63% patients with metastatic disease, respectively." (PMID 18822183, 2008). "For metastatic disease, frontline combination strategies, such as osimertinib plus chemotherapy (FLAURA2) and amivantamab plus lazertinib (MARIPOSA), building on the EGFR-TKI backbone have improved progression-free and overall survival, particularly in higher-risk subgroups." (PMID 41438982, 2025). "STATEMENT 57—Alternative therapeutic options including radiotherapy, chemotherapy, electrochemotherapy or targeted therapy with EGFR inhibitors should be considered when surgical excision is not feasible, and in locally advanced or metastatic disease." (PMID 40091088, 2025). "Alternative therapeutic options including radiotherapy, chemotherapy, electrochemotherapy or targeted therapy with EGFR inhibitors should be considered when surgical excision is not feasible, and in locally advanced or metastatic disease." (PMID 40091088, 2025). "Additionally, 348 (68.5 %) received bevacizumab, 148 (29.1 %) received anti-EGFR therapy, 115 (22.6 %) received Trifluridine/Tipiracil (Lonsurf), and 12 (2.4 %) received BRAF inhibition during their treatment for metastatic disease." (PMID 40184716, 2025). "In GEMSTONE-302 [NCT03789604], eligible patients had histologically or cytologically confirmed stage IV squamous or non-squamous NSCLC without known EGFR sensitizing mutations, ALK, ROS1, or RET fusions, no previous systemic treatment for metastatic disease." (PMID 38241591, 2024). "The majority of targeted compounds, for example, EGFR, BRAF and MET inhibitors, as well as molecules directed towards rearranged kinases, are particularly effective when administered in the very beginning of the treatment of metastatic disease." (PMID 38966170, 2024). "Eligible patients were characterized by metastatic non-squamous NSCLC without sensitizing EGFR or ALK mutations, and had not been previously treated for metastatic disease." (PMID 38241591, 2024).
metastatic disease (continued). "The best known is cetuximab, a chimeric IgG1 monoclonal antibody that binds to the extracellular domain of the EGFR membrane and is approved in combination with radiotherapy for the treatment of advanced HNSCC and as monotherapy for locoregional recurrence and metastatic disease." (PMID 36982894, 2023). "During these years, only 2281 person-years of EGFR- and ALK-targeted therapies were dispensed to Medicaid patients, suggesting that an estimated 66% of Medicaid patients with EGFR- and ALK-altered metastatic disease received indicated targeted therapies across all states." (PMID 36696113, 2023). "In metastatic disease, BRAF V600E-mt confers resistance to EGFR inhibitor therapy." (PMID 35323316, 2022). "Indeed, cetuximab which is an epidermal growth factor receptor (EGFR) monoclonal antibody, has been approved by FDA as a radiation-sensitizer, alone or in combination with chemotherapy for patients with recurrent or metastatic diseases." (PMID 35081970, 2022). "The EGFR monoclonal antibody Cetuximab is approved by the FDA as a radiation sensitizer, alone or in combination with chemotherapy, for treating patients with recurrent or metastatic disease." (PMID 36012290, 2022). "MiRNAs are involved in different molecular pathways of the carcinogenesis of colorectal cancer such as the Wnt/β-catenin, TGF-β and EGFR pathways or epithelial-to-mesenchymal transition (EMT), and are correlated with the evolution of metastatic disease or with the efficacy of systemic treatments." (PMID 36230757, 2022). "For metastatic disease, CMS4 cancers are resistant to anti-EGFR therapy, regardless of the state of the KRAS mutation." (PMID 36230757, 2022). "At the time of EGFR-TKI treatment initiation in the first-line setting, nine patients (9.4%) had locally advanced and 87 (90.6%) had metastatic NSCLC, while a total of 89 patients had metastatic disease at the time of progression in the first-line setting." (PMID 34202063, 2021). "Importantly, the expression of STAMBP, EGFR in cell membrane and phosphorylated ERK in cell nucleus was markedly reduced in the STAMBP knockdown tumor tissues from the lung and metastatic tumors from the chest wall." (PMID 34102455, 2021). "The most common sites of distant metastatic disease in the EGFR-wildtype group were lung (n = 9; 43%), lymph nodes (n = 9; 43%), and brain (n = 5; 24%)." (PMID 32523650, 2020). "We identified EGFR as a potential target of miRNA-134 and miRNA-4328, for non-metastatic and metastatic tumors, respectively." (PMID 32170146, 2020). "Here, we also identified miR-134 and miR-4328 as negatively regulated EGFR targets in non-metastatic and metastatic tumors, respectively." (PMID 32170146, 2020). "We found potential interactions of two miRNAs targeting EGFR expression, (miR-134 and miR-4328, in non-metastatic and metastatic tumors, respectively)." (PMID 32170146, 2020). "In contrast, we found no EGFR mutations in plasma cfDNA from 14 NSCLC patients with resectable mutant EGFR-positive tumours, or in 3 of the 17 patients (18%) with metastatic disease whose tumours probably did not shed enough DNA for molecular detection." (PMID 30953094, 2019). "Approximately 40% of patients with CRC will eventually develop metastatic disease; per international guidelines, the majority of these patients should undergo RAS testing for suitability for an anti-EGFR mAb in combination with oxaliplatin- or irinotecan-based chemotherapy." (PMID 31616627, 2019). "PCa patients with altered levels of EGFR mRNA expression in their primary or metastatic tumors suffered poorer DFS compared to those without alterations in EGFR expression." (PMID 30134822, 2018). "The results showed that no statistical differences in the frequencies of EGFR, KRAS, HER2, BRAF, and PIK3CA mutations and other GMs were observed between unpaired primary and metastatic tumors." (PMID 29518290, 2018).
metastatic disease (continued). "Although EGFR and HER2-targeted therapy has substantial activity in EGFR and HER2-overexpressing malignancies, respectively, therapeutic resistance and progression eventually develops in responders with metastatic disease who remain on therapy." (PMID 30092835, 2018). "Distribution of EGFR reactivity and polysomy/amplification was similar between different tumour sizes and independent of metastatic disease." (PMID 28377929, 2017). "Survival benefit from EGFR-targeted therapy appeared greater among patients with locally advanced rather than metastatic disease (R = −0.69, p < 0.001)." (PMID 28445400, 2017). "EGFR‐TKI such as erlotinib, gefitinib, and afatinib have shown clinical activity toward NSCLC, leading to their approval for the treatment of metastatic disease." (PMID 28003335, 2017). "In 18 patients with metastatic disease (stage IV) treated by anti-EGFR (cetuximab or panitumumab), the disease control rate was not influenced by the polyA tract polymorphism (p = 0.78)." (PMID 23565769, 2013). "Despite high overall expression levels of EGFR positivity in our cohort, EGFR was not shown to be predictive of nodal disease at presentation or of development of distant metastatic disease." (PMID 24401183, 2013). "The presence of either high polysomy, low polysomy or trisomy of EGFR does not appear to correlate with metastatic disease (p = 0.6)." (PMID 23056620, 2012). "The metastatic disease treatment targeting EGFR is found to be efficient only if KRAS and BRAF are not mutated." (PMID 21103049, 2010). "In addition to these findings, a significant decrease in serum expression of EGFR was observed between the diagnoses of PBC and of metastatic disease." (PMID 17976236, 2007). "A major criticism that should be made to all studies on predictive markers of clinical response to anti-EGFR agents in MCRC, including ours, is that the clinical response is evaluated on the metastatic disease whereas the presence of the molecular marker is assessed from the primary tumour." (PMID 17375050, 2007). "Notably, prior studies investigating anti-EGFR therapy were conducted in patients with metastatic disease who did not undergo curative surgery." (PMID 40428735, 2025). "The majority of discordant cases concerned surgery (12.3%), radiotherapy (16.7%), and chemoradiotherapy (11.6%), but not patients with metastatic disease (0%), while it remained unclear whether EGFR status or immunotherapy affected concordance." (PMID 40075729, 2025). "ESMO guidelines do not recommend local treatments with radical intent for EGFR-mutated and ALK-rearranged metastatic disease if it is not in the oligoprogressive scenario (see paragraph below), though the level of evidence is low due to the lack of randomised data." (PMID 39996875, 2025). "Yet, the number of patients was restricted considerably because no prior systemic therapy for advanced/metastatic disease was allowed, other than EGFR TKIs, and in some countries, chemotherapy was often used due to delays in EGFR TKIs authorizations by the Health Insurance Houses during 2015–2017." (PMID 36005198, 2022). "Despite a response of short duration in patients with mCRC, the inclusion of anti-EGFR therapy to chemotherapy with FOLFOX or FOLFIRI has been shown to increase response rates and convert patients with inoperable liver disease to potentially resectable metastatic disease." (PMID 33562755, 2021). "Along the same lines, a more limited metastatic spread with less extrapulmonary metastatic sites, as well as a better ECOG PS for secondary (relapsed) vs. de novo metastatic tumors have also been noted by other investigators, who analyzed unselected NSCLC patients regardless of EGFR mutation status." (PMID 33898315, 2021). "EGFR expression could be regulated by amplification or polysomies (in metastatic tumors), or miRNAs (miRNA-134, in non-metastatic tumors)." (PMID 32170146, 2020).
metastatic disease (continued). "It should be noted that none of the non-metastatic tumors showed ≥35% positivity for EGFR antibody." (PMID 32170146, 2020). "One explanation for this discrepancy is that these agents are used in metastatic diseases and EGFR protein expression of the primary tumor may not accurately reflect the status of the metastatic tissue." (PMID 32155907, 2020). "All cases showing loss of MLH1 (20% of cases) and PMS2 (25%) expression, and absence of CEA expression (22% of cases) were non-metastatic tumors; most liver metastatic tumors had a positive value of EGFR membranous expression (79% vs. 38% of non-metastatic cases)." (PMID 32170146, 2020). "Main eligibility criteria included primary disease in the oral cavity, hypopharynx, nasopharynx, oropharynx, or larynx; no prior history of EGFR-directed therapy; receipt of Cmab plus chemotherapy as first-line therapy for recurrent or metastatic disease; and follow-up for more than 90 days." (PMID 30619755, 2018). "Similarly, our RNA-seq data demonstrated that EGFR was not significantly overexpressed in primary or metastatic tumors compared with normal liver." (PMID 28486549, 2017). "In conclusion, these preclinical data confirm the enormous potential of EGFR-targeted synthetic polymers for systemic NIS gene delivery in an advanced multifocal CRC liver metastases model and open the exciting prospect of NIS-mediated radionuclide therapy in metastatic disease." (PMID 29190908, 2017). "Recent therapeutic approaches that add epidermal growth factor receptor (EGFR) and vascular endothelial growth factor (VEGF) targeted agents to standard chemotherapy have produced a prolonged overall survival (OS) of up to 30 months in patients with metastatic disease." (PMID 28635639, 2017). "Monoclonal antibody therapies that target epidermal growth factor receptor (EGFR), including cetuximab (Erbitux, ImClone, LLC) and panitumumab (Vectibix, Amgen), are becoming widely used approaches 2, particularly for patients with chemorefractory metastatic disease." (PMID 24890702, 2014). "Cetuximab (Erbitux®; Imclone Systems Inc./Bristol-Myers Squibb) and panitumumab (Vectibix®; Amgen Inc.)are anti–epidermal growth factor receptor (EGFR) monoclonal antibodies that may be used for first-, second- or third-line treatment in patients with metastatic disease." (PMID 20972475, 2010). "However, most patients with recurrent or metastatic disease in our study were not treated with EGFR monoclonal antibodies because they were mostly treated between 2004 and 2007." (PMID 20184776, 2010). "Moreover, while for metastatic disease, CMS4 tumors are resistant to anti-EGFR therapies (irrespective of KRAS mutational status) and to doublet/triplet backbone chemotherapy, the benefit of adjuvant treatment for early and locally advanced CMS4 tumors is not obvious." (PMID 34201502, 2021). "Next-generation sequencing revealed that these lesions harbored a common somatic mutation in epidermal growth factor receptor (EGFR), c.3617A>C, which is not considered a pathogenic chordoma mutation, thus indicating that these lesions were not multicentric but rather multiple metastatic tumors." (PMID 33312743, 2020). "Similarly, our study found that the frequencies of EGFR, KRAS, HER2, BRAF, and PIK3CA mutations in TKI‐naive samples and the frequencies of sensitizing EGFR and T790M mutations in TKI‐relapsed samples showed no statistical differences between unpaired primary and metastatic tumors." (PMID 29518290, 2018). "Therefore, identification of EGFR mutations in only primary tumors may not be representative of the EGFR mutation status of other metastatic lesions; as a result, tyrosine kinase inhibitor (TKI) treatment may have different effects on primary and metastatic tumors." (PMID 24212826, 2011).
metastatic disease (continued). "Additionally, we demonstrated that the male gender, initial metastatic disease, adrenal metastasis, and the absence of intrathoracic metastasis impacted PFS negatively in patients with EGFRm mNSCLC who received EGFR-TKI treatment in the present study." (PMID 40004680, 2025).